RN7SKP297 (RN7SK pseudogene 297)
Gene: Miscellaneous RNA gene on chromosome 11 (74,685,224 to 74,685,505, forward strand). Ensembl gene ENSG00000223202.
Homologues: Orthologues: chimpanzee 7SK (95% identical), mouse Gm54392 (67% identical). Paralogues in human: RN7SKP9 (78% identical), RN7SKP37 (77% identical), RN7SKP1 (76% identical), RN7SKP189 (76% identical), RN7SKP246 (76% identical), RN7SKP255 (76% identical), RN7SKP78 (76% identical), 7SK (75% identical), RN7SKP176 (75% identical), RN7SKP217 (75% identical), RN7SKP50 (75% identical), RN7SKP159 (75% identical), and 283 more.